APOE (apolipoprotein E)
Diseases named in the same sentence as APOE in open-access papers (continued):
Sharing a sentence is not in itself a finding about the gene and the disease.
Alzheimer disease (continued). "Thus, being overweight by BMI standards may preserve hippocampal function, but obesity reduces hippocampal structure and function in older African Americans with the APOE-ε4 Alzheimer’s disease risk allele." (PMID 37731955, 2023). "There is a common three-allele APOE polymorphism: APOE*2, APOE*3, and APOE*4, resulting in six genotypes (2/2,2/3,2/4,3/3,3/4,4/4), and it has a profound effect on determining interindividual variation in plasma cholesterol level and in determining Alzheimer’s disease (AD) risk." (PMID 37666928, 2023). "Three APOE isoforms, created by the ε2, ε3, and ε4 alleles with two single-base changes (APOE rs7412 and APOE rs429358) in the coding region of APOE, are the most well-defined common variants that determine plasma lipid levels, coronary risk, and Alzheimer disease." (PMID 36011277, 2022). "Finally, we consider colocalization of LDL cholesterol and Alzheimer disease risk at the genetic region 100 kilobasepairs either side of the APOE gene (chr19:45,409,011–45,412,650 on hg19 by Ensembl) where cis-Mendelian randomization suggests a causal relationship." (PMID 35452592, 2022). "Future studies may also assess the polygenic risk for Alzheimer's disease using common (e.g., APOE) and rare variants associated with the disease, which would help disentangle environmental and psychosocial risk factors from genetic risk factors contributing to cognitive frailty's etiology." (PMID 35012965, 2022). "Therefore, we examined whether APOE ɛ4 and sex modify cross-sectional associations between cardiovascular risk and tau deposition in cognitively normal older adults from the Alzheimer’s Disease Neuroimaging Initiative." (PMID 35233525, 2022). "Finally, the rate of change of brain volume (or atrophy acceleration) may be sensitive to Alzheimer’s disease-polygenic risk beyond APOE in healthy individuals (t = 2, P = 0.04)." (PMID 36523268, 2022). "For example, ADAPTED was focused on understanding the contribution of the apolipoprotein E (APOE) genetic risk factor to Alzheimer's disease, developing human cell models with disrupted APOE expression and investigating samples and data from patients with Alzheimer's disease." (PMID 36408524, 2022). "However, the contribution of APOE may account for less than 20% of the risk of late-onset Alzheimer’s disease (LOAD)." (PMID 36552141, 2022). "This study examined whether MB and MV in high-fat diets, affected microbiota composition and gut–blood–brain markers in apolipoprotein E deficient (ApoE-/-) rats, a model for studies of lipid-associated disorders, and neurodegenerative processes in Alzheimer’s disease (AD)." (PMID 36104381, 2022). "Speculation includes a common genetic background linking psoriasis to Alzheimer's disease (AD), i.e., the APOE-ε4 allele, cardiovascular risk factors especially the metabolic syndrome, and tumor necrosis factor-α because of its role in neural functions as well as in inflammation." (PMID 35937394, 2022). "Altered ApoE isoform-specific high-density lipoprotein formation and its supply to neural cells via ApoE receptors may be causes of the altered cholesterol metabolism in the Alzheimer’s disease (AD) brain." (PMID 34721384, 2021). "Our results present a trajectory of hippocampal volume that may inform critical periods before accelerated hippocampal volume loss creates an environment making those already at risk of Alzheimer’s disease (APOE e4/e4 older females) highly vulnerable to a cascade of neurodegenerative processes." (PMID 33615215, 2021). "Interestingly, the APOE ε4 allele is also associated with decreased selenium in the brain, again suggesting a possible role for selenium and selenoproteins in preventing Alzheimer's disease." (PMID 34277682, 2021).
Alzheimer disease (continued). "In addition, there is evidence that ApoE ε4 is associated with a variety of neuropsychiatric symptoms (e.g., depression, anxiety, apathy, agitation, aggression, hallucinations, and delusions) in patient with Alzheimer’s disease." (PMID 34930329, 2021). "For example, ApoE is the strongest known risk gene for late-onset Alzheimer disease; Rajabli and colleagues (2018) showed that variation in risk for Alzheimer disease across populations may be at least partially explained by the ancestral background interacting with the risk allele." (PMID 33705374, 2021). "Therefore, we aim to explore whether there are sex-related associations of CSF ApoE and AD biomarkers using Alzheimer’s Disease Neuroimaging Initiative (ADNI) database." (PMID 33746700, 2021). "Interestingly, the Alzheimer disease (AD) subjects carrying ApoE ɛ4 allele had lower ApoA1 levels but higher ApoB levels and there were differences in biomarker levels (e.g., cholesterol, LDL, and ApoB) for each ApoE genotype with reference to ε3ε3 in a UK Biobank study." (PMID 34930329, 2021). "Our hypothesis is that hippocampal subfields will differ in their relative preservation, versus decline, in volume from mid to late life, showing a steeper trajectory associated with Alzheimer’s disease risk factors of female sex, older age and APOE e4 positive status." (PMID 33615215, 2021). "As mentioned in a previous report showing a higher hippocampal loss in the presence of APOE-ε4, the authors suggested that increased brain volume loss could be an indicator of Alzheimer's disease pathology and a potential marker for the efficacy of therapeutic interventions in Alzheimer's disease." (PMID 34721251, 2021). "However, while the APOE ε4 allele confers significantly increased risk of developing Alzheimer’s disease (AD), the APOE ε2 allele is hypothesized to be protective against the development of AD." (PMID 32961217, 2021). "Similarly, the highly active chromosome 19 contains genes such as APOE and Notch 3, whose polymorphisms have implications in, respectively, Alzheimer’s disease (AD) and stroke and dementia associated with cerebral autosomal dominant arteriopathy with subcortical infarcts and leukoencephalopathy." (PMID 33805201, 2021). "Similarly, two uploads could reveal any genotype at a single site of interest, such as rs429358, which reveals whether the user carries an APOE-ε4 variant and is associated with risk of late-onset Alzheimer’s disease." (PMID 31908268, 2020). "Moreover, it has been shown that homozygous carriers of the ApoE ε4 allele have a more than 10-fold increased risk of developing Alzheimer’s disease, possibly due to increased cholesterol levels, altered brain development early in life or increased oxidative brain damage." (PMID 32846900, 2020). "However, it is worth noting that the noise variable affecting X determines the prevalence of the APOE ε4 allele, while the noise variable affecting Y contributes to the definition of the causal mechanism between the APOE ε4 allele status and Alzheimer’s disease." (PMID 32615926, 2020). "Single nucleotide polymorphisms (SNPs) in Apolipoprotein E (APOE) are known to increase risk for developing Alzheimer’s disease, however there is controversy from human and rodent studies as to whether ApoE4 is a risk factor for worse outcomes after brain trauma." (PMID 33199792, 2020). "Each additional copy of the apolipoprotein E4 (APOE4) allele is associated with a higher risk of Alzheimer’s dementia, while the APOE2 allele is associated with a lower risk of Alzheimer’s dementia, it is not yet known whether APOE2 homozygotes have a particularly low risk." (PMID 32015339, 2020).
Alzheimer disease (continued). "Lipoprotein clearance may play an important role in Alzheimer’s disease pathogenesis through the association of APOE and several other genes that function in lipid or lipoprotein metabolism, including Clusterin (CLU) and ATP binding cassette (ABC) transporter A7 (ABCA7,)." (PMID 32299494, 2020). "Apolipoprotein E (APOE) is a protein that plays an important role in lipid metabolism (including cholesterols) and has been implicated in synaptogenesis, repair of injured nerve tissue and the modulation of beta-amyloid plaques and neurofibrillary tangles that characterise Alzheimer’s disease (AD)." (PMID 33088920, 2020). "In the early nineties, it was discovered that the specific e4 allele of Apolipoprotein E (APOEε4) was associated with both early- and late-onset dementia, supporting the hypothesis that Alzheimer’s disease was the predominant cause of both early- and late-onset dementia." (PMID 31212802, 2019). "Genetically, apolipoprotein E (APOE) ε4 allele status alters PCA risk but with a smaller effect than for typical Alzheimer’s disease and an exploratory genome-wide association study has identified three candidate genetic risk factors that may be specific to PCA." (PMID 31219516, 2019). "Here, we conducted a sub-analysis of MRI data and test scores from the same RCT to determine whether anserine/carnosine supplementation specifically benefits elderly people carrying the APOE e4 allele, which is a risk gene for accelerated brain aging and for the onset of Alzheimer’s Disease." (PMID 29896423, 2018). "For example, if there are genetic variants that are likely to be outliers or influential points (such as variants in the APOE gene region for Alzheimer’s disease or in the FTO gene region for BMI), then an outlier-robust approach may be more appropriate than the MR-Egger method." (PMID 29709202, 2018). "Some studies have estimated that carriers of the ApoE-ԑ4 allele may have a 42% higher risk of cardiovascular disease than carriers of the ApoE-ԑ3/ԑ3 genotype; they also have a greater risk of Alzheimer’s disease, and in general the genotype is negatively associated with longevity." (PMID 30518135, 2018). "Finally, several authors argue that the association between APOE genotype and cognitive decline may be due to confounding from pre-clinical Alzheimer’s disease." (PMID 30339707, 2018). "APOE-ε4 has been shown to be a strong genetic risk factor for amyloid pathology (e.g., β-amyloid deposition, subsequent neuroinflammation and microglia activation) in Alzheimer’s disease; however its association with tauopathies—the typical pathological hallmark of CTE—is less clear." (PMID 30223506, 2018). "Additionally, apoE has been shown to have a strong genotype-dependent association with risk and age of onset for the development of sporadic and late-onset forms of Alzheimer’s disease (AD); apoE4 is associated with the highest risk whereas apoE2 has been suggested to be protective." (PMID 29579087, 2018). "Moreover, the alleles of the ApoE gene, specifically e4, could be further researched for an effect on post-concussion cognitive dysfunction due it their potential connection to Alzheimer’s disease and CTE." (PMID 29910309, 2018). "Despite the important role of apolipoprotein E (apoE) secretion from astrocytes in brain lipid metabolism and the strong association of apoE4, one of the human apoE isoforms, with sporadic and late onset forms of Alzheimer’s disease (AD) little is known about the regulation of astrocytic apoE." (PMID 29579087, 2018). "The frequency of the APOE-e4/e4 genotype among registrants is higher than in the general population, at 4.47%, and the APOE-e4 allele frequency is 20.4%; among the 3,456 registrants asked about whether they had a family history of dementia or Alzheimer disease, 70.1% said yes." (PMID 28323826, 2017).
Alzheimer disease (continued). "Association between APOE ε4 and longevity for example might be mediated by Alzheimer’s disease; healthy older individuals are less likely to carry the APOE ε4 gene variant, thus they have a smaller risk for Alzheimer’s disease, which further prolongs their life expectancies." (PMID 27992450, 2016). "Thus, interaction between CHAT rs3810950 polymorphism and ApoE-ε4 allele could be a huge risk factor for Alzheimer's disease." (PMID 27597977, 2016). "Our data is consistent with the idea that Alzheimer's disease constitutes a failure of neurons to sustain the levels of βAPP and dynactin-P50 necessary for the increased demands imposed by aging, especially in combination with other risk factors such as inheritance of APOE ε4." (PMID 25859183, 2015). "Apolipoprotein E (ApoE, encoded by the APOE gene), a protein involved in both exogenous and endogenous lipid metabolism, plays a significant role in the process of age-related diseases, including cardiovascular diseases, Alzheimer's disease, and age-related macular disease." (PMID 25476875, 2015). "Moreover, NPC patients carrying Apolipoprotein E (APOE) ε4 alleles develop extracellular cerebral deposition of β-amyloid (Aβ) peptides, a characteristic pathological feature of Alzheimer’s disease (AD), the most common type of senile dementia affecting the elderly." (PMID 23382922, 2013). "Furthermore, APOE-4 allele dose modulates hippocampal volume in Alzheimer's disease patients." (PMID 24228185, 2013). "The ApoE ε4 allele is associated with increased risk and earlier onset of Alzheimer disease (AD), and conversely the ApoE2 allele is protective against AD." (PMID 21822496, 2011). "Since the alleles of the APOE gene, which modulate peripheral cholesterol metabolism, and midlife plasma cholesterol are both associated with Alzheimer's disease (AD) risk, we have evaluated the hypothesis that SNPs associated with plasma cholesterol are also associated with AD." (PMID 21867541, 2011). "To date, we do not have a functional SNP or haplotype that has made a credible contribution to our understanding of disease pathogenesis in the way that the APOE-e4 allele does in Alzheimer disease (AD) and the H1 MAPT haplotype does in parkinsonian syndromes." (PMID 19740415, 2009). "We examined their correlation with demographic factors (age, sex, apolipoprotein E status), markers of Alzheimer's disease pathology, neurodegeneration, neuroinflammation, and mean diffusivity." (PMID 41884594, 2026). "As a proof of concept, we applied DuAL-Net to 14,094 SNPs within the APOE ±50-kb region from 1,050 individuals in the Alzheimer's Disease Neuroimaging Initiative and Alzheimer's Disease Sequencing Project (ADSP) cohorts." (PMID 41971952, 2026). "BACKGROUND: Humanized APOE targeted-replacement (TR) mice are essential tools for studying apoE isoform effects in Alzheimer’s disease (AD) and other apoE-related disorders." (PMID 41877131, 2026). "Structural equation modeling (SEM) was applied to disentangle direct and indirect relationships among APOE ε4, temporal clinical parameters, Alzheimer's disease-related pathologies, and ALS TDP-43 subtype." (PMID 42141160, 2026). "While the contribution of ApoE isoforms to neurodegenerative disorders, most notably Alzheimer's disease, has been described in considerable detail, their impact on peripheral physiology is far less clearly defined." (PMID 42253927, 2026). "Alzheimer's disease (AD), particularly its sporadic form (SAD, 95 % AD patients), is strongly associated with the apolipoprotein E4 (ApoE4) genotype and characterized by oxidative stress, iron dysregulation, and increased susceptibility to ferroptosis." (PMID 41760425, 2026). "The mechanisms by which apolipoprotein E (APOE) drives copathologies in established Alzheimer's disease (AD) dementia via amyloid-dependent versus age-driven pathways remain unresolved." (PMID 41890856, 2026).
Alzheimer disease (continued). "The pathogenesis of Alzheimer’s disease is modulated by APOE status and other genetic factors; a range of cardiovascular risk factors; and lifestyle and environmental risk factors." (PMID 40647320, 2025). "Previous research on ApoE predominantly focused on Alzheimer's disease and the cardiovascular field." (PMID 40495209, 2025). "We also confirmed the APOE locus (rs429358, P < 5.0 × 10–8), a known risk locus for DLB and Alzheimer’s disease in Caucasians." (PMID 40045203, 2025). "Single-cell validation confirmed vascular-endothelial dysfunction, with LAMC1, RBMS2 and TMOD3 upregulated in endothelial cells from female APOE ε4 Alzheimer’s disease brains." (PMID 41409615, 2025). "With the rising importance of lipid droplets in Alzheimer’s disease, we aimed to systematically characterize the proteome and lipidome of lipid droplets in astrocytes harboring different APOE genotypes." (PMID 40894647, 2025). "Menopausal hormone therapy (MHT), along with the apolipoprotein E (APOE) ε4 allele, has been suggested as a possible risk factor for Alzheimer's disease (AD)." (PMID 39783876, 2025). "In conclusion, our study provides evidence of the role of insulin resistance measured by the TyG in modulating BBB permeability in Alzheimer's disease, in relation to APOE genotype, with APOE e4/e4 displaying a higher BBB permeability." (PMID 39992249, 2025). "One subgroup of APOE ε4/ε4 subjects had unexpectedly low ApoE4 levels, raising questions about potential biological heterogeneity and its impact on Alzheimer’s disease biology." (PMID 40671162, 2025). "Mean age at death and 95% confidence intervals according to apolipoprotein E genotypes in the overall sample and participants with Alzheimer`s disease pathology by cognitive status and race." (PMID 41268805, 2025). "Our findings revealed variations in fluid biomarker levels from the two APOE subgroups, which indicated the different roles of APOE genotypes in the progression of Alzheimer's disease." (PMID 39749650, 2025). "For example, the endocytosis of apolipoprotein E (apoE), which binds to LDLRs, influences the accumulation and the clearance of amyloid β peptide, a key factor in the progression of Alzheimer’s disease." (PMID 40574019, 2025). "Apolipoproteins are known to influence several pathways involved in neurodegeneration in Alzheimer’s disease; namely, apolipoprotein E interacts with presenilin." (PMID 41516203, 2025). "Among these, 13 individuals were identified as homozygous for apolipoprotein ε4 (apoE ε4), with 46% of them diagnosed with Alzheimer’s disease." (PMID 41303353, 2025). "Methods of assessment vary widely, ranging from cognitive tests such as the Mini-Mental State Examination (MMSE) and the Consortium to Establish a Registry for Alzheimer’s Disease (CERAD) test to conduct genetic analyses of APOE genotypes." (PMID 40650110, 2025). "Growing evidence suggests a connection between insulin resistance and apolipoprotein E (APOE) genotype in Alzheimer's disease (AD) pathogenesis, but the mechanisms are unclear." (PMID 39992249, 2025). "For example, in Alzheimer’s disease, interactions between APOE genotype and air pollutant exposure can significantly affect the rate of cognitive decline." (PMID 40640928, 2025). "Here, the authors show that the APOE isoforms show different transcriptomic and epigenomic responses to amyloid, by studying human microglia transplanted into the brain of an Alzheimer’s disease mouse model." (PMID 40419479, 2025). "The strongest genetic drivers of late‐onset Alzheimer's disease (AD) are apolipoprotein E4 (ApoE4) and TREM2R47H." (PMID 40219843, 2025). "We identified vincamine, a vasodilator, as a top candidate that significantly counteracts the transcriptional profile of female APOE ε3/ε4 Alzheimer’s disease (AD) patients." (PMID 41409615, 2025).